PCDH11Y (protocadherin 11 Y-linked)
Description:
Potential calcium-dependent cell-adhesion protein.
Synonyms: PCDH22; PCDHY; PCDH-PC; PCDHX
Tractability: Antibody: UniProt places it where antibodies can reach, with high confidence; UniProt predicts a signal peptide or a membrane-spanning region; its Gene Ontology location is reachable by antibodies, with medium confidence.
Gene: Protein-coding gene on chromosome Y (5,000,226 to 5,742,224, forward strand). Ensembl gene ENSG00000099715.
Subcellular location: Cell membrane
Subcellular location (Human Protein Atlas): Plasma membrane; Cytosol; Vesicles
Gene Ontology:
Molecular function: cell adhesion molecule binding; calcium ion binding
Biological process: cell adhesion; homophilic cell-cell adhesion
Cellular component: plasma membrane; membrane
Homologues: Orthologues: chimpanzee PCDH11X (98% identical), macaque PCDH11X (93% identical), mouse Pcdh11x (82% identical), rat Pcdh11x (81% identical), tropical clawed frog pcdh11x (60% identical), zebrafish pcdh11 (55% identical). Paralogues in human: PCDH11X (98% identical), PCDH9 (51% identical), PCDH1 (35% identical), PCDH7 (34% identical), PCDH20 (24% identical), CDH23 (18% identical), DCHS1 (18% identical), DCHS2 (17% identical), CDHR2 (16% identical), CDH2 (15% identical), CDH1 (14% identical), CDHR1 (14% identical), and 21 more.
Diseases named in the same sentence as PCDH11Y in open-access papers:
PCDH11Y is named in the same sentence as 10 diseases in open-access papers, as found by Europe PMC text mining. Sharing a sentence is not in itself a finding about the gene and the disease. The quoted sentences say what the papers report.
prostate carcinoma (3 papers, 2014 to 2025). A carcinoma that arises from epithelial cells of the prostate gland. "One of the nicotine suppressed targets PCDH11Y is a gene on the human Y chromosome that is known to be selectively expressed in apoptosis and hormone-resistant human prostate cancer cells." (PMID 25401222, 2014). "This novel circRNA, derived from the PCDH11Y gene, a gene involved a gene involved in the androgen-independent prostate cancer cell growth and neuroendocrine trans-differentiation, was highly upregulated during trans-differentiation, suggesting its potential role as a biomarker for t-NEPC." (PMID 40008007, 2025). "Examples include PCDHB9 in gastric cancer, PCDHGC5 in astrocytomas, and PCDH11Y in prostate cancer." (PMID 32694982, 2020).
autism (1 paper, 2011). Persistent deficits in social interaction and communication and interaction as well as a markedly restricted repertoire of activity and interest as well as repetitive patterns of behavior. "Genome association studies have shown that single-nucleotide polymorphisms and deletions in Pcdh genes, such as PCDH10, PCDH11Y and PCDH12, are associated with bipolar disorder, schizophrenia and autism, respectively." (PMID 21824415, 2011).
glioblastoma (1 paper, 2015). The most malignant astrocytic tumor (WHO grade IV). "Other examples include the two cadherin domain instances encoded by PCDH11X and PCDH11Y in glioblastoma." (PMID 25794154, 2015).
language delay (1 paper, 2016). "For example, deletion of this gene was found in a patient with developmental dyslexia, and deletion of both PCDH11X and PCDH11Y was discovered in a child with non-syndromic language delay." (PMID 26759715, 2016).
tumor (4 papers, 2016 to 2026). "For instance, PCDH8 and PCDH20 are considered tumour suppressors, while PCDH11Y functions as an oncoprotein." (PMID 35864095, 2022).
cancer (3 papers, 2021 to 2025). A tumor composed of atypical neoplastic, often pleomorphic cells that invade other tissues. "Our attention was focused on thecircPCDH11Y, the circular RNA derived from PCDH11Y gene, a gene involved in the androgen-independentprostate cancer cell growth and neuroendocrine trans-differentiation." (PMID 40008007, 2025). "In order to explore only genes related to cancer, we selected four genes, including three that were upregulated via copy number gain (ANOS1, ETV1, and XPNPEP2) and one gene (PCDH11Y) that was downregulated via copy number loss." (PMID 33470396, 2021).
PCDH11Y also shares sentences with these, for which no sentence is quoted: amelogenesis imperfecta (1 paper); bipolar disorder (1); psychiatric diseases (1); schizophrenia (1).